MIR449A (microRNA 449a)
Synonyms: hsa-mir-449; hsa-mir-449a; MIRN449; MIRN449A; mir-449a
Gene: MicroRNA gene on chromosome 5 (55,170,532 to 55,170,622, reverse strand). Ensembl gene ENSG00000198983.
Pathways (Reactome):
Signal Transduction: Pre-NOTCH Transcription and Translation
Gene Ontology:
Biological process: miRNA-mediated post-transcriptional gene silencing
Homologues: Orthologues: chimpanzee ptr-mir-449a (99% identical), macaque mml-mir-449a (99% identical), dog MIR449A (93% identical), rat Mir449a (88% identical), guinea pig MIR449A (87% identical), mouse Mir449a (86% identical), tropical clawed frog xtr-mir-449a (60% identical). Paralogues in human: MIR449B (52% identical).